APP (amyloid beta precursor protein)
Diseases named in the same sentence as APP in open-access papers (continued):
Sharing a sentence is not in itself a finding about the gene and the disease.
Headache (1 paper, 2022). Cephalgia, or pain sensed in various parts of the head, not confined to the area of distribution of any nerve. "In the clinical, a higher prevalence of headaches in MCs is held for different PSEN1 and APP mutations and electrophysiological features related to longer latencies of the N100, P200, N200, and P300 components, and smaller slow wave amplitudes." (PMID 35959289, 2022).
hereditary dementia (1 paper, 2017). An instance of dementia that is caused by an inherited genomic modification in an individual. "Furthermore, the present study demonstrates for the first time that mutation-induced loss of APP function could be a cause of recessive hereditary dementia." (PMID 28760161, 2017).
herpesvirus infection (1 paper, 2005). "However to date the effects of acute herpesvirus infection on metabolism of APP in human neuronal-type cells have not been investigated." (PMID 16109164, 2005).
Hirschsprung disease (1 paper, 2022). Hirschsprung disease (HSCR) is a congenital intestinal motility disorder that is characterized by signs of intestinal obstruction due to the presence of an aganglionic segment of variable extent in the terminal part of the colon. "Previously, we identified several BACE2 rare variants in Hirschsprung disease (HSCR) patients and proved that BACE2-mediated APP cleavage might represent a novel HSCR pathogenesis mechanism in enteric nervous system." (PMID 35110536, 2022).
Hyperammonemia (1 paper, 2022). An increased concentration of ammonia in the blood. "Together, these data suggest that hyperammonemia triggers neuroinflammation and neurodegeneration, as well as elevation of APP and Aβ levels in astrocytes." (PMID 35427648, 2022). "To examine whether increased ammonia production is involved in the pathogenesis of AD in vivo, we intraperitoneally injected NH4Cl (5 mmol kg−1) in C57BL6/J mice, an acute model of hyperammonemia, and investigated its effect on APP." (PMID 35427648, 2022).
hypoxia (1 paper, 2017). A decrease in the amount of oxygen in the body. "Cerebral hypoxia is associated with lower CSF levels of amyloid precursor protein (APP) metabolites." (PMID 28583116, 2017).
infarction (1 paper, 2013). A localised pathological necrosis of tissue resulting from obstruction of the blood supply usually by a thrombus, an embolus, or vascular torsion. "The difference in the incidence of various types of infarction between APP severity levels was significant (P<0.01)." (PMID 24137198, 2013). "The results of statistical analysis by χ2 test revealed that the difference in the incidence of various types of infarction between APP severity levels was significant (χ2=39.52, P<0.01)." (PMID 24137198, 2013). "The difference in the incidence of various types of infarction between APP severity levels was significant (χ2=39.52, P<0.01)." (PMID 24137198, 2013).
inflammatory breast carcinoma (1 paper, 2022). An advanced, invasive breast adenocarcinoma characterized by the presence of distinct changes in the overlying skin. "Aβ (amyloid beta) and it's precursor APP can be observed in tumors formed by mouse xenograft model of human inflammatory breast cancer (IBC)." (PMID 34592066, 2022).
invasive breast carcinoma (1 paper, 2014). A carcinoma that infiltrates the breast parenchyma. "However, the vast majority of the invasive breast carcinomas showed some degree of APP expression." (PMID 25491510, 2014).
iron metabolic disorders (1 paper, 2018). "Studies have demonstrated that iron metabolic disorders can induce the production and accumulation of Aβ because iron can act on the IRE site of APP mRNA, thereby enhancing the translation and expression of endogenous APP." (PMID 30250423, 2018).
kidney cancer (1 paper, 2024). Primary or metastatic malignant neoplasm involving the kidney. "gDS showed that APP deletion slightly affects several kidney cancer cells’ viability, which reduces the possibility of APP acting as a target in kidney cancer." (PMID 38728235, 2024).
language disorder (1 paper, 2021). A category of disorders characterized by an impairment in the development of an individual's language capabilities, which is in contrast to his/her non-verbal intellect. "The fourth language disorder, lvPPA, did not share any of its four genes (APOE, APP, GRN, MAPT) with the other disorders." (PMID 34539327, 2021).
latent infections (1 paper, 2021). "Most of these studies reveal that latent infections from viruses such as HSV and HIV pose a major risk factor for AD by inducing alterations to the amyloid precursor protein (APP)-processing homeostasis." (PMID 33401749, 2021).
Lissencephaly (1 paper, 2012). A spectrum of malformations of cortical development caused by insufficient neuronal migration that subsumes the terms agyria, pachygyria and subcortical band heterotopia. "Interestingly, FE65 and FE65L double knockout mice exhibit defects similar to triple APP knockout (APP tKO): lissencephaly and selected axonal projection defects." (PMID 22429478, 2012).
lung disease (1 paper, 2021). "However, the role of APP on macrophages and lung disease has not been reported." (PMID 33478018, 2021).
male infertility (1 paper, 2020). The inability of the male to effect fertilization of an ovum after a specified period of unprotected intercourse. "In oxidative stress mediated male infertility aberrant expression of APP results in acrosome dysfunction." (PMID 32372034, 2020).
Menkes disease (1 paper, 2017). A usually severe multisystemic disorder of copper metabolism, characterized by progressive neurodegeneration and marked connective tissue anomalies as well as typical sparse abnormal steely hair. "Copper depleted human fibroblasts due to overexpression of the Menkes disease protein, presented with a downregulation of APP gene expression and decreased APP protein concentrations." (PMID 28459846, 2017).
metachromatic leukodystrophy (1 paper, 2024). A rare lysosomal storage disorder characterized by intralysosomal accumulation of sulfatides in various tissues, leading to progressive deterioration of motor and neurocognitive function. "For instance, among genetic mutations linked to known hNDDs, examples include HTT gene mutation in HD, SOD1 in amyotrophic lateral sclerosis, PSEN1, PSEN2, and APP in AD, ARSA gene mutation in metachromatic leukodystrophy (MLD), and others." (PMID 39200370, 2024).
metastatic tumours (1 paper, 2021). "The expression of APP, on the other hand, decreases in both primary and metastatic tumours., We found TRIM25 to be indirectly targeted by all the compounds, except in MDA-MB-231 under indole-3-carbinol." (PMID 34193143, 2021).
migraine (1 paper, 2020). "In APPDutch mice (overexpressing the E693Q APP mutation) neuronal expression of APPDutch leads to cerebrovascular amyloidosis, hemorrhage and smooth muscle cell degeneration, supportive of the idea that vasculopathy may be implicated in migraine." (PMID 32503413, 2020).
MODY (1 paper, 2015). "Knock-downs of proteins involved in “Maturity onset diabetes of the young”, or MODY, have different effects on APP proteolytic products." (PMID 25723573, 2015).
Moyamoya disease (1 paper, 2013). Moyamoya disease (MMD) is a rare intracranial arteriopathy involving progressive stenosis of the cerebral vasculature located at the base of the brain causing transient ischemic attacks or strokes. "Using the novel functional interpolating single-nucleotide polymorphisms bioinformatics approach, we identified 6 Moyamoya Disease-associated autoantibodies against APP, GPS1, STRA13, CTNNB1, ROR1 and EDIL3." (PMID 23518061, 2013).
Myoclonus (1 paper, 2022). Very brief, involuntary random muscular contractions occurring at rest, in response to sensory stimuli, or accompanying voluntary movements. "We also performed genotype-phenotype analysis according to the difference in APP processing caused by the mutations, and we found that there were indeed differences in onset age, behavioral and psychological disorders of dementia (BPSD) and myoclonus." (PMID 36313020, 2022).
myopia (1 paper, 2019). "Targets of γ-secretase include APP (amyloid precursor protein) and APLP-2 (amyloid beta precursor-like protein-2); the latter protein has been linked to myopia development through an interaction with time spent reading." (PMID 31073882, 2019).
myositis (1 paper, 2023). "Investigating TDP-43 overexpression or extracellular aggregates in myotubes would shed light on whether non-inflammatory myositis features can trigger muscle inflammation, for which there is evidence for the sIBM-related protein β APP." (PMID 37731843, 2023).
nasal polyps (1 paper, 2024). "We also identified protective variants such as APP p.Ala673Thr (rs63750847, P = 7 × 10−11) reducing odds of developing AD, and ALOX15 p.Thr560Met protecting against nasal polyps (rs34210653, P = 2 × 10−15)." (PMID 39563277, 2024).
nematode infection (1 paper, 2023). "GFAP and APP staining was not present in the brains of control mice, relatively weak in nematode-infected mice or mice given LPS and strongest in mice given both LPS and nematode infection." (PMID 37762297, 2023).
neural tumors (1 paper, 2025). "This paradoxical effect reflects the broader complexity of APP-related pathways in neural tumors, where proteins canonically associated with neurodegeneration may paradoxically support tumor aggressiveness." (PMID 41003874, 2025).
neuroendocrine tumors (1 paper, 2019). "Like human neuroendocrine tumors, mouse SCLC (mSCLC) lacked cell surface MHC-I and exhibited low expression of multiple MHC-I APP genes, which were induced following genetic disruption or pharmacological inhibition of PRC2." (PMID 31564637, 2019).
neurosyphilis (1 paper, 2024). Infection of the brain or spinal cord by Treponema pallidum. "Furthermore, vascular damage and chronic inflammation may influence amyloid precursor protein (APP) processing, potentially exacerbating amyloid deposition, though this connection is less well-documented in neurosyphilis." (PMID 39728746, 2024).
nonseminomatous germ cell tumors (1 paper, 2016). "APP expression was detected in ∼39% of nonseminomatous germ cell tumors (NSGC), and APP was associated with venous invasion." (PMID 26840089, 2016).
Opportunistic infection (1 paper, 2009). An infection that is caused by a pathogen that would generally not be able to cause an infection in a host with a normal immune system. "The mechanisms underlying the reduced CSF sAPPs in both ADC and the opportunistic infections are uncertain but may relate to the well-documented brain deposition of APP in both frank HIVE and in brains without identified foci of HIV infection." (PMID 20028512, 2009).
oral cancer (1 paper, 2023). "However, when APP/PS1 combination was compared with APP/PS1 + PE, we identified 772 DEGs, which were found to be enriched in EIF3K and REST transcription factors, both shown to regulate the mTOR signaling pathway in adipocyte yeast and oral cancer cells, respectively." (PMID 39081972, 2023).
Osteopenia (1 paper, 2018). Osteopenia is a term to define bone density that is not normal but also not as low as osteoporosis. "The upregulated proteins from SDEs of osteopenia, such as amyloid precursor protein (APP), NCL, and VCAN, interact with proteins implicated in cellular adhesion and formation of osteoclasts." (PMID 29603567, 2018). "The most important proteins that were found to be upregulated in SDEs of osteopenia patients were amyloid precursor protein (APP), nucleolin (NCL), and members of the cytoplasmic ribosomal proteins." (PMID 29603567, 2018).
ovarian failure (1 paper, 2025). "The purpose of the current study was to investigate the effects of chemically induced ovarian failure in mice on time‐course adaptations in cognition, APP processing, and synaptic markers." (PMID 39711362, 2025). "In the HIPP, protein content was not significantly different between groups when looking at total APP, sAPPα, sAPPβ, BACE1, the sAPPα/sAPPβ ratio, nor was BACE1 and ADAM10 enzyme activity affected by ovarian failure (P > 0.05)." (PMID 39711362, 2025).
parathyroid adenomas (1 paper, 2025). "Second, transcriptomic analyses of parathyroid adenomas show an inverse relationship between APP and VDR RNA expression." (PMID 40492090, 2025).
Pleuritis (1 paper, 2019). Inflammation of the pleura. "Not performing an empty period between batches was positively associated with pleuritis and APP seropositivity in the swine herds, reinforcing the idea that all-in/all-out management is an important procedure in the prevention of respiratory diseases." (PMID 31636919, 2019).
pneumonia (1 paper, 2005). An acute, acute and chronic, or chronic inflammation focally or diffusely affecting the lung parenchyma, caused by an infection in one or both of the lungs (by bacteria, viruses, fungi, or mycoplasma.). "Interestingly, infection of human brain microvascular endothelial cells with Chlamydia pneumonia (Cpn) may increase the intensity of a similar 55 kDa C-terminal APP band (personal communication, Professor Brian Balin, PA, USA)." (PMID 16109164, 2005).
primary immunodeficiency (1 paper, 2023). "In the present study, we found that CTG, which encodes leucine, was the most preferred codon in APP, CCND1, and PTPA, as well as in genes common to primary immunodeficiency and cancer." (PMID 37383425, 2023).
progeria (1 paper, 2022). "In conclusion, our study demonstrates that inhibition of the ATases restores proteostatic functions within the ER and can rescue the disease phenotype of AT-1 sTg, a mouse model of segmental progeria, and APP/PS1, a mouse model of AD." (PMID 35217767, 2022).
psoriasis vulgaris (1 paper, 2021). Plaque psoriasis is the most common presentation of psoriasis. "Acitretin, a retinoid-derivative and approved treatment for Psoriasis vulgaris,increases non-amyloidogenic Amyloid-Precursor-Protein-(APP)-processing, prevents Aβ-production and elicits cognitive improvement in AD mouse models." (PMID 34315969, 2021).
rectal cancer (1 paper, 2024). A primary or metastatic malignant neoplasm that affects the rectum. "Interestingly, in our study, decreased APP expression was associated with reduced CRC risk in the US, European, and Israel populations, but a reverse effect was observed in Asian populations (Chinese and Japanese) and rectal cancer." (PMID 38243058, 2024).
severe acute respiratory syndrome (1 paper, 2022). A viral respiratory infection caused by the SARS coronavirus. "A meta-analysis was conducted utilizing QIAGEN Ingenuity Pathway Analysis (IPA) to examine the link between severe acute respiratory syndrome-coronavirus-2 (SARS-CoV-2) and the modulation of APP expression upon virus binding the Angiotensin-converting enzyme-2 (ACE2) receptor." (PMID 35163117, 2022).
Spinocerebellar ataxia type 3 (1 paper, 2022). "In animal models of spinocerebellar ataxia type 3 (SCA3) and Alzheimer's disease (AD), UBE4B facilitates clearance of ataxin 3 and APP, respectively." (PMID 36440598, 2022).
squamous cell carcinoma (1 paper, 2009). A carcinoma arising from squamous epithelial cells. "Forced expression of AP-2α in keratinocytes causes increased expression of the oncogene Amyloid Precursor Protein (APP), and these two genes have both been found to be increased in squamous cell carcinomas." (PMID 19742317, 2009).
swine influenza (1 paper, 2012). An acute viral respiratory infection caused by a strain of influenza virus which is endemic in swine (pigs). "Further evidence of exposure to at least one other pathogen tested for (APP, swine influenza, PCV2) on PRRSV positive farms was common; 53.3% of PRRSV positive farms also tested positive for H1N2, 31.1% for avian-like H1N1, 84.8% for APP and 89.1% for PCV2." (PMID 23034160, 2012).
testicular germ cell tumor (1 paper, 2013). A germ cell tumor arising from the testis. "In a testicular germ cell tumor (TGCT), a recent study suggested an association of APP expression in transformed human pluripotent stem cells." (PMID 23662100, 2013). "The biological role of amyloid precursor protein (APP) is not well understood, especially in testicular germ cell tumors (TGCTs)." (PMID 23662100, 2013).
trigeminal neuralgia (1 paper, 2021). Trigeminal neuralgia is a nerve disorder that causes a stabbing or electric-shock-like pain in parts of the face. "APP processing can occur via a non-amyloidogenic or an amyloidogenic pathway and occurs at cell surfaces and in trigeminal neuralgia, in which APP is transported to cell surfaces and endosomal compartments." (PMID 34066808, 2021).
trisomy (1 paper, 2024). A chromosomal abnormality consisting of the presence of one chromosome in addition to the normal diploid number. "Here we find that antisense oligonucleotides (ASOs) targeting APP are an effective approach to reduce APP protein levels and rescue endolysosome and autophagy dysfunction in APP duplication and Trisomy 21 human induced pluripotent stem cell (hiPSC)-derived cortical neurons." (PMID 38527856, 2024).
trisomy 16 (1 paper, 2013). "OX-LDL and LDL induced significant increases in trisomy 16 in both cell types, indicating that the aneugenic effect of lipoproteins is independent of APP expression and Aß production." (PMID 23593294, 2013).
ulcers (1 paper, 2023). "This, accompanied by the high abundance of amyloid-beta precursor protein (APP), apolipoprotein E (APOE), MADD (MAP kinase-activating death domain protein), ATF6B, ERN1 and TRAP1 in the presence of ulcers, shows that, along with cell death, the epithelial health maintenance response is strong." (PMID 37170213, 2023).
undifferentiated pleomorphic sarcoma (1 paper, 2025). An undifferentiated soft tissue sarcoma characterized by the presence of a pleomorphic malignant cellular infiltrate. "Experimental data on anti-MIF and anti-APP oncotherapy already exists, with vaccination targeting of APP being discussed as a therapy for several cancers and anti-MIF treatment having potential for treatment of undifferentiated pleomorphic sarcoma." (PMID 41373578, 2025).
Urinary incontinence (1 paper, 2017). Loss of the ability to control the urinary bladder leading to involuntary urination. "These include tau oligomerization, tangle formation, gliosis and APP accumulation, as well as prevention of sensorimotor coordination deficits and urinary incontinence." (PMID 29042562, 2017).
Vascular insufficiency (1 paper, 2019). "Vascular insufficiency results in hypoperfusion and hypoxia that activate the amyloid precursor protein (APP) cleavage enzyme β-secretase and facilitates a robust deposition of fibrillar amyloid." (PMID 31293412, 2019).
Williams syndrome (1 paper, 2021). "Particularly, EIF4H is one of the genes deleted within 7q11.23 in patients with Williams Syndrome, which shares some phenotypic characteristics seen in ASD, while altered levels of APP and its metabolites have been identified in brain and plasma from autistic patients." (PMID 32060413, 2021).
xerostomia (1 paper, 2020). Dryness of the mouth resulting from reduced salivary secretion. "The decreased expression of APP in SS sufferers with xerostomia compared to HS can reflect the loss of APP neuroprotective function and the cholinergic deficiency in SS related xerostomia." (PMID 33066537, 2020). "Results indicate their role in the endoplasmic reticulum system, their overlapping function and the loss of the APP neuroprotective function in xerostomia." (PMID 33066537, 2020). "In SS patients both with xerostomia (sicca) and without xerostomia (non-sicca), TMED10, PDIA4, CANX, APP, and TMBIM6 expression was lower than in HS." (PMID 33066537, 2020).